BCL2 (BCL2 apoptosis regulator)
Diseases named in the same sentence as BCL2 in open-access papers (continued):
Sharing a sentence is not in itself a finding about the gene and the disease.
cancer (continued). "Venetoclax is a Bcl-2 antagonist that mimics the BH3 domain of pro-apoptotic Bcl-2 family members, thus antagonizing the anti-apoptotic Bcl-2 protein and enabling the activation of the effectors Bak and Bax on the mitochondrial surface of Bcl-2 dependent cancer cells." (PMID 41213958, 2025). "Subsequently, western blot analyses revealed that the downregulation of MESP1 expression led to an increase in Bax protein levels, a decrease in Bcl2 protein levels, enhanced cancer cell apoptosis rate, suppression of EMT, and a reduction in metastasis of PC cells." (PMID 40610403, 2025). "By integrating Bcl-2 inhibitors with epigenetic drugs, immune modulators, kinase blockers, and proteasome inhibitors, researchers and clinicians are beginning to dismantle the complex survival networks that cancer cells depend on." (PMID 40841912, 2025). "Additionally, results for other drug sensitivity markers (ABCG2, ABCB1, BCL2; P < 0.00001) and cancer stem cells (CSCs) markers (ALDH1A1, PROM1; P < 0.01) were also presented." (PMID 40264043, 2025). "However, overexpression of Bcl-2 in cancer cells inhibits cell death pathways, resulting in lower effectiveness of anticancer drugs." (PMID 41502528, 2025). "Following dendrimer PEGylation (PEG5000 modified with a synthetic luteinizing-hormone-releasing hormone (LHRH) analogue) provided greater particle stability and active targeting to specific cancer cells, which led to increased intratumoral accumulation and enhanced suppression of Bcl-2 mRNA." (PMID 40166479, 2025). "In cancers such as cervical, thyroid, and glioblastoma, it further promotes intrinsic apoptotic signaling, increases intracellular calcium levels, and shifts the Bax/Bcl-2 ratio in favor of apoptosis." (PMID 40869364, 2025). "Interestingly, Nur77 shifts the function of Bcl-2 protein from anti-apoptotic to pro-apoptotic, facilitating the treatment of various diseases, including cancer 23-25." (PMID 39744474, 2025). "The dysregulation of apoptosis is due in part to the overexpression of Bcl-2 in cancer cells." (PMID 40565145, 2025). "Notably, PTX/miR-34a@C–HA/C–PEI PCNs effectively downregulated critical oncogenic targets, including Notch1, Snail1, and BCL-2, resulting in reduced cancer cell migration and proliferation." (PMID 40869286, 2025). "Members of the BCL‐2 gene family function as key regulators of apoptotic activity with the potential to be leveraged to enable the more effective treatment of PCa and other forms of cancer." (PMID 40344485, 2025). "Our findings that FN combined with anticancer drugs further upregulated the BAX/BCL-2 and cleaved caspase-9/caspase-9 ratios relative to drug treatment alone support the hypothesis that FN sensitizes cancer cells to apoptosis." (PMID 41614757, 2025). "The intrinsic apoptosis pathway, which is tightly regulated by pro- and anti-apoptotic BCL2 proteins that interact on the mitochondrial outer membrane, is an attractive area of cancer biology that demonstrates promise as a target for novel therapeutic strategies in lethal PCa." (PMID 41438049, 2025).
cancer (continued). "However, the anti-tumor activity of AT101 in GECs relies primarily on targeting the cancer stem cells pathway, which remains active when BCL2 is downregulated." (PMID 40075071, 2025). "Therefore, TIS cancer cells with a common senescence-like phenotype show a highly variable response to the dual BCL-2/BCL-XL inhibitor ABT-263/navitoclax." (PMID 40055336, 2025). "This could enhance Bcl-2 degradation and apoptosis, particularly in resistant cancer cells where XIAP and Bcl-2 are overexpressed." (PMID 40841912, 2025). "Notably, treatment with PTX and 6-Glucan resulted in the downregulation of BCL2, Survivin, MMP7, and TGF-β in sorted MDA-MB-231 CSC mammospheres, indicating a decrease in gene expression levels associated with these cancer-related processes." (PMID 39955575, 2025). "This suggests that BCL-2 may inhibit apoptosis, enabling the survival of cancer cells and facilitating the accumulation of complex and adverse genetic mutations." (PMID 40699745, 2025). "UA inhibits papillary thyroid carcinoma (IHH-4 and TPC-1) cells by classical mechanisms, which inhibits EMT by down-regulating fibronectin-1 (FN1), blocks invasive behaviors of cancer cells, reduces the protein expression of Bcl-2, and activates Caspase-3, which further promotes apoptosis [1065]." (PMID 40490812, 2025). "In addition, cancer cells often evade apoptosis by upregulating anti-apoptotic proteins such as Bcl-2 and other inhibitors of apoptosis proteins (IAPs)." (PMID 41007213, 2025). "Given that inhibition of Bcl-2 can enhance the apoptotic sensitivity of cancer cells, this compound may be considered a potential apoptotic inducer." (PMID 40699727, 2025). "Suppressing Survival Signals: It lowers Bcl-2 levels, a protein that helps cancer cells survive." (PMID 40649942, 2025). "By directly targeting BCL-2, miR-34a encourages cancer cells to undergo apoptosis." (PMID 40227645, 2025). "It is increasingly evident that targeting Bcl-2 proteins may provide new avenues for cancer therapy." (PMID 40227591, 2025). "Additionally, the equilibrium between anti-apoptotic (Bcl-2 for instance) and proapoptotic (Bax and Bak) proteins is disturbed in cancer cells: the concentration of proapoptotic ones is reduced, while the expression of anti-apoptotic proteins is increased." (PMID 40142969, 2025). "This raises the question of whether antiapoptotic inhibitors truly act as senolytics by targeting Bcl-2/XL in TIS cancer cells or through an alternative, yet unidentified mechanism." (PMID 40312750, 2025). "Importantly, both DMC (SN7) and its dimers (SN5–SN6), which were also identified in S. nervosum seeds in the previous studies, have been shown to exert pro-apoptotic effects by suppressing Bcl-2 and activating caspase-3 in cancer cells." (PMID 40725071, 2025). "It was also found that the application of curcuminoid to cancer cells raised the expression of the apoptotic‐related proteins Bak and Bax, while decreasing the expression of the anti‐apoptotic protein components of Bcl‐2." (PMID 41179371, 2025). "The decrease in Bcl-2 and increase in Bax confirmed apoptosis in cancer cells, indicating that miR-497/SK-NBs treatment may boost CTL-mediated cytotoxicity through the mitochondrial apoptosis pathway." (PMID 41583493, 2025). "In cancer cell lines such as MDA-MB-231, MDA-MB-453, and 4T1 (mouse mammary carcinoma cell line), ICA promoted mitochondrial apoptosis by upregulating cleaved caspase-3 and Bax while downregulating Bcl-2, which led to a loss in ΔΨm and increased ROS." (PMID 39796234, 2025).
cancer (continued). "In our study, we found that IL‐17 secreted from NPC‐Exos‐induced γδT‐17 cells significantly upregulated the expression of anti‐apoptotic protein BCL‐2, which could promote radioresistance of cancer cells." (PMID 39901895, 2025). "Targeting BCL-2 has been a significant strategy in cancer drug development." (PMID 41465610, 2025). "Additionally, they suppress anti‐apoptotic proteins like Bcl‐2 while increasing pro‐apoptotic molecules such as Bax, further promoting cancer cell death." (PMID 40538987, 2025). "Current research suggests that small molecule antagonists targeting BCL-XL and MCL-1 could improve outcomes for cancers resistant to BCL-2 inhibition." (PMID 40204952, 2025). "Furthermore, in various cancer cells, overexpression of Bcl-2 inhibits BAX/BAK-dependent pore formation, resulting in resistance to anticancer therapies." (PMID 41226559, 2025). "Sequential administration of cisplatin followed by navitoclax, a BCL-2/BCL-XL inhibitor, has shown promising preclinical results by selectively inducing apoptosis in senescent cells, thus potentially reducing the risk of cancer recurrence." (PMID 40563615, 2025). "The downregulation of Bcl-2 and Bcl-xL genes in cancer cells, combined with the plant’s inhibitory activity against α-glucosidase and α-amylase, provides new insights into its traditional uses and positions it as a promising source for future therapeutic development." (PMID 41465738, 2025). "ABT.263 (Navitoclax) is a targeted inhibitor of BCL-2, which can induce cancer cell to apoptosis." (PMID 40740228, 2025). "We further explored whether NOXA upregulation could enhance sensitivity to BCL-2 inhibitors in cancer cells." (PMID 40699886, 2025). "Targeting this proteasome-Bcl-2 axis holds immense promise to usher in a new era of cancer therapy." (PMID 40841912, 2025). "As a result, the Bcl2 transcriptional control has become a popular target for cancer therapies." (PMID 40353245, 2025). "The development of numerous cancers, including OSCC, is linked to the antiapoptotic protein BCl-2.2, 31Apoptosis is the most significant mechanism of cell death in response to malignancy therapy and is mostly regulated by BCl-2." (PMID 39348855, 2025). "The inhibition of this pathway by 1C suggests that this compound may act as a BCL-2 inhibitor, leading to the induction of apoptosis in cancer cells." (PMID 40286078, 2025). "BH3 mimetics, for example, venetoclax, designed to restore apoptotic sensitivity by inhibiting Bcl-2, may be efficacious only in apoptosis-resistant cancers (Montero and Haq, 2022)." (PMID 40166425, 2025).
cancer (continued). "While BCL2 overexpression generally indicates poor prognosis due to enhanced cell survival and resistance to apoptosis, these findings underscore the complex role of BCL2 in cancer prognosis and warrant further investigation." (PMID 41156312, 2025). "In the context of cancer, NF-κB signaling might protect the cells from apoptosis by inducing the activation of anti-apoptotic proteins such as Bcl-2, IAP-1, and -2 and promote their growth by regulating components in cell cycle machinery." (PMID 40799801, 2025). "Furthermore, elevated expression of BAX and a concomitant reduction in BCL‐2 were observed in the combination treatment group, suggesting an augmentation of cancer cell apoptosis through this combinatorial approach." (PMID 41020311, 2025). "The ratio of Bcl-2 to Bax determines the activity and death of cancer cells." (PMID 40276535, 2025). "Additionally, galangin mitigates cisplatin resistance in lung cancer (A549) cells by suppressing the p-STAT3/p65 and Bcl-2 signaling pathways, further demonstrating its potential as therapeutic agent in resistant cancer." (PMID 41195268, 2025). "In general, when an anticancer agent could induce apoptosis in cancer cells, a decrease in the levels of anti‐apoptotic Bcl‐2 proteins and an increase in the levels of pro‐apoptotic protein (Bax) are observed." (PMID 40666823, 2025). "Similarly, VEN specifically inhibits the anti-apoptotic protein BCL2, which is mainly increased in cancer cells." (PMID 39531065, 2025). "The compound's effects on Bcl‐2 downregulation and Bax upregulation, alongside caspase activation, suggest an effective anti‐cancer mechanism that may reduce resistance development." (PMID 40245183, 2025). "The upregulation in BAX expression, but downregulation in BCL2 expression in cancer therapies may indicate that cells are directed to apoptosis." (PMID 40576246, 2025). "Our findings suggest that disrupting the WSB2–NOXA axis could synergize with BCL-2 inhibitors to induce apoptosis in cancer cells, offering a novel strategy for combating apoptosis resistance in human cancers." (PMID 40699886, 2025). "Moreover, an increase of BAX/BCL-2 ratio in both cancer cells clearly supported the fact that these cells undergo apoptosis after BNHLE treatment." (PMID 40362409, 2025). "In addition to modulating the Bcl2-to-Bax ratio and caspase-3 levels, it blocked the growth of tumors by causing caspase-3-mediated cell death in a TRAM cancer model." (PMID 40143065, 2025). "The properties of latently HIV-1-infected cells may resemble those of cancer cells expressing high level of BCL-2, allowing ABT-263-sensitive cell death." (PMID 40392781, 2025). "Additionally, DHX33 has been found to stimulate Bcl-2 transcription in many human cancer cell lines." (PMID 39886381, 2025). "This might imply that the cancer cells have maintained their resistance to apoptosis through a consistent Bcl-2 expression." (PMID 38987732, 2024). "In addition, a morphological analysis of the lymph nodes obtained from Balb-c mice with NHL and a molecular docking study using proteins related with cancer, namely, Bcl-2, Mcl-1 and VEGFR-2, were performed." (PMID 38731446, 2024). "We tested whether the created model could illustrate changes in the BCL2 PPI network as AML underwent clonal cancer evolution." (PMID 39025942, 2024). "BCL-2 is an anti-apoptotic gene that helps cancer cells evade cell death mechanisms." (PMID 38195537, 2024). "NK cells effectively drive cancer cells toward mitochondrial apoptosis, and when combined with the BCL-2 inhibitor venetoclax, they synergistically enhance the killing of cancer cells both in vitro and in vivo while pre-activated NK cells have been shown to become resistant to venetoclax." (PMID 39544945, 2024). "BCL2 is widely recognized as a multifunctional anti-apoptotic protein in various types of cancer." (PMID 39011503, 2024).
cancer (continued). "The interplay between ERBB2 and its direct targets MYC, PTEN, and BCL2 creates a robust network that collaboratively impacts cancer cell biology by promoting proliferative signaling, evading growth suppressors, resisting cell death, and facilitating invasion and metastasis." (PMID 39409883, 2024). "Y. Zhou and his colleagues found that calycosin (100 μM) inhibited SK‐0V‐3 cancer cell growth, proliferation and induced apoptosis via upregulating production of cleaved caspase‐3, cleaved caspase‐9, Bax/Bcl‐2 ratio and downregulating expression of Bcl‐2, pro‐caspase‐3, pro‐caspase‐9 signaling." (PMID 38230908, 2024). "Bcl-2 is an anti-apoptotic prosurvival protein that is overexpressed in many cancer cells." (PMID 39252711, 2024). "In some RS cases (e.g., RSVR3, RS1050, RS1316), MCL-1, BCL-xL, and BFL-1 exerted a prominent role in protecting cancer cells from apoptosis, suggesting their direct targeting might be effective and outperform BCL-2 antagonism." (PMID 38724507, 2024). "Thus, our results provide a promising and rational combination, that is, radiation plus BCL2 inhibitors, for cancer treatment." (PMID 38316463, 2024). "This indicates that BCL2 has a significant role in pan cancer analysis and could be a common target for cancer treatments." (PMID 39040139, 2024). "In cancer tissue, Bcl2 showed marked expression, while Bax revealed mild expression." (PMID 38072891, 2024). "Previous research showed that miRNA-21’s regulation might be adjusted to increase cancer cell apoptosis by modulating many target genes involved in cell apoptosis, such as BCL2 and PTEN." (PMID 38592437, 2024). "Their hypothesis was confirmed subsequently by multiple studies on the Bcl-2/Bax ratio as a clinical prognostic marker of cancer." (PMID 39234106, 2024). "The novelty of this research lies in its integration of traditional Chinese medicine (TCM) with advanced computational drug discovery techniques to address a critical challenge in cancer therapy: the suppression of Bcl-2 protein, widely known in cancer cell survival." (PMID 38978121, 2024). "Moreover, the process of apoptosis is very complex and tightly regulated by the coordination of distinct mediators, including Bcl-2, which negatively impacts apoptotic events; therefore, it is considered the preferred target in the management of cancer." (PMID 39410048, 2024). "Venetoclax can inhibit the Bcl‐2 and disrupting the survival signals of cancer cell." (PMID 38800967, 2024). "These siRNA-target genes are mainly those that promote cell differentiation and proliferation and inhibit apoptosis, which are overexpressed in cancer cells, such as Bcl-2, survivin, epidermal growth factor receptor (EGFR), Janus kinase 1 (JAK1), and polo-like kinase 1 (PLK1)." (PMID 39407665, 2024). "The significance of Bcl-2 in angiogenesis and cancer development has been extensively established." (PMID 38978121, 2024). "This may be a unique yet feasible mechanism supporting the treatment of cancer patients with BCL-2 inhibitors." (PMID 38062129, 2024). "In recent years, the search for molecules that bind to the BH3 domain on Bcl-2 and Mcl-1 has been proposed, as it could be promising for the therapy of cancers and some types of NHL with the overexpression of these proteins." (PMID 38731446, 2024). "The t-DARPP expression promotes antiapoptotic function in cancer cells by upregulating Bcl2." (PMID 38308500, 2024). "For instance, cancer cells can recognize apoptotic signals induced by chemotherapeutic agents and overexpress proteins such as Bcl-2, IAP, and Akt to inhibit apoptosis, or they can overexpress proteins like P-gp to eject the drugs from the cell, resulting in reduced efficacy." (PMID 39274842, 2024).